RNF146 (ring finger protein 146)
Diseases named in the same sentence as RNF146 in open-access papers (continued):
Sharing a sentence is not in itself a finding about the gene and the disease.
tumor (7 papers, 2012 to 2025). "Whilst the frameshift deletion in RNF146 seemed to be restricted to this particular tumour, a similar yet germline mutation in ZNF407 was found in a panel of 52 gastro-intestinal stromal tumours from different anatomical sites and different categories." (PMID 26102504, 2015). "We could not exclude a priori the possibility that any of the mutations in the relatively uncharacterised genes RNF146 or ZNF407 was linked to the formation of the tumor." (PMID 26102504, 2015). "Besides these genetic lesions, only two point mutations that may affect tumour progression were identified: A frame-shift deletion in RNF146 and a missense mutation in a zinc finger of ZNF407." (PMID 26102504, 2015). "RNF146 is regulated by tumor-suppressive miRNAs miR-306 and miR-79, which target RNF146 mRNA, reducing its expression." (PMID 40001540, 2025). "RNF146 mediates PARdU-dependent degradation of key tumor suppressors such as AXIN1/2 and PTEN, thereby promoting tumorigenesis." (PMID 40001540, 2025). "Western blot assays showed that RNF146 protein expression increased in human GC tissue samples paired with adjacent non‐tumour tissues (5/8, 62.5%) as well as in most GC cell lines compared to that in the gastric normal epithelial mucosa cell line GES‐1." (PMID 37555915, 2023). "We also found that miR‐3133, as an upstream regulator of RNF146, plays a tumour‐suppressive role in GIC." (PMID 37555915, 2023). "IHC staining of Ki-67 in tumor tissues indicated that the percentage of positive cells in the RNF146 knockdown group was obviously lower than in the control group (p < 0.05)." (PMID 35721496, 2022). "There were correlations between the expression of RNF146 and tumor size (P = 0.044), histological type (P = 0.005), poor differentiation (P = 0.002), lymphatic metastasis (P = 0.009), and pTNM stage (P = 0.015)." (PMID 24454854, 2014). "In the present study, RNF146 regulated Axin and β-catenin of the Wnt signaling pathway, indicating that RNF146 affected the proliferation and invasion of tumor cells." (PMID 24454854, 2014). "As miR‐3133 was found to be a negative regulator of RNF146, we hypothesized that miR‐3133 may act as a tumour‐suppressive miRNA in tumorigenesis and progression." (PMID 37555915, 2023). "Additionally, the knockdown efficiency of RNF146 in the xenograft tumours was further confirmed after the excision of the tumour mass." (PMID 37555915, 2023). "miR-306 and mir-79 suppress tumor growth and promote cell competition by targeting RNF146." (PMID 36222503, 2022). "In addition to regulating the growth and survival of tumor cells, RNF146 played tumor-enhancing roles and affected the migration and invasion of tumor cells in NSCLC." (PMID 24454854, 2014). "RNF146 expression correlated with tumor size, differentiation level, lymphatic metastasis, pTNM staging, and prognosis of patients in stage I. RNF146 expression was negatively correlated with Axin expression but positively correlated with the nuclear expression of β-catenin in NSCLC tissues." (PMID 24454854, 2014). "Moreover, it seems that RNF146 mutations are not commonly associated with GIST since the studied tumour remains the only example among a panel of 21 samples of various GIST types." (PMID 26102504, 2015). "Thus, it can be concluded that RNF146 controls tumor proliferation by regulating the cell cycle." (PMID 24454854, 2014). "The results revealed that the expression of YAP1 and its downstream target genes was markedly decreased in RNF146‐knockdown HGC‐27 cells and xenograft tumours." (PMID 37555915, 2023). "In vivo experiments were performed by injecting RNF146‐knockdown HGC‐27 cells into the armpit of BALB/C‐nude mice, and the xenograft tumours were measured for 28 days." (PMID 37555915, 2023). "RNF146 results in the ubiquitination and degradation of PTEN to activate the AKT pathway and promotes tumor cell proliferation and glycolysis." (PMID 35721496, 2022).
tumor (continued). "Together, these data indicate that miR-306 and miR-79 directly target RNF146 mRNA, thereby enhancing JNK signaling activity and thus exerting the tumor-suppressive effects." (PMID 36222503, 2022). "RNF146 mediates the ubiquitination and degradation of PTEN to activate the AKT pathway and promotes tumor cell proliferation and glycolysis." (PMID 35721496, 2022). "Studies have suggested a possible correlation between the newly identified E3 ubiquitin ligase ring finger protein 146 (RNF146) and tumor development." (PMID 24454854, 2014). "Overexpression of miR-306 or miR-79 in JNK-activated tumor cell results in overactivation of JNK signaling to the lethal level via RNF146-Tnks-mediated noncanonical JNK-activating signaling." (PMID 36222503, 2022). "However, until now, studies on RNF146 have been restricted to poly(ADP-ribosyl)ation and ubiquitin ligation, whereas the role of RNF146 in tumor biology has rarely been reported." (PMID 24454854, 2014).
adenocarcinoma (1 paper, 2014). A common cancer characterized by the presence of malignant glandular cells. "The expression of RNF146 protein in the LTE (adenocarcinoma) and LK2 (squamous) cell lines were moderate, and the expression of RNF146 protein in the A549 and H1299 (adenocarcinoma) cell lines were high." (PMID 24454854, 2014).
bacterial infection (1 paper, 2018). "Our analysis revealed downregulation of miRNA-150 during bacterial infection may exert broad effects on metabolism (SLCA2A3/GLUT3), cytokine regulation (SOCS1), and cell signaling pathways (MAPK13, IPO8, ACVR1B, RNF146) consistent with the host response to bacterial infection." (PMID 30619110, 2018).
RNF146 also shares sentences with these, for which no sentence is quoted: Osteopenia (2 papers); breast (1); Intellectual disability (1); metabolic disease (1); neurological diseases (1); teratocarcinoma (1).